ICOS (inducible T cell costimulator)
Diseases named in the same sentence as ICOS in open-access papers (continued):
Sharing a sentence is not in itself a finding about the gene and the disease.
lymphoma (12 papers, 2013 to 2025). A malignant (clonal) proliferation of B- lymphocytes or T- lymphocytes which involves the lymph nodes, bone marrow and/or extranodal sites. "Moreover, CD25highCD127low/neg Tregs, including activated ICOS+ Tregs, can suppress conventional T cells, with their generation linked to ICOS/ICOSL interactions with lymphoma B cells." (PMID 41190308, 2025). "Parallel observations could be drawn by future studies testing the association of CARD11 mutations with increased PD-1 or ICOS expression on human T-lymphoma cells." (PMID 36960072, 2023). "CD4 + EM3 T cells (cluster 9), expressing ICOS and PD-1, were enriched in lymphoma patients, except those who had received CT alone." (PMID 40630518, 2025). "Ectopic expression of miR21 of lymphoma cells significantly increased ICOS expression on Treg cells in both co-culture systems of SU-DHL-4 and SU-DHL-8 cells (P = 0.036 and P = 0.015)." (PMID 28637496, 2017). "Our data suggested that CD8+ Tfr cells might engage with lymphoma B cells and DCs via ICOS/ICOSL interactions, potentially stabilising FOXP3 function but also increasing IL‐10 production by Tregs, enhancing suppressive potency." (PMID 41190308, 2025). "Additionally, in vivo ROR1.ICOS.OX40ζ T-cells showed anti-lymphoma activity, a long-lasting central memory phenotype, improved overall survival, and evidence of long-term CAR T-cell persistence." (PMID 37719008, 2023). "An inguinal LN biopsy appeared as a tumor-cell-rich AITL, with abundant lymphoma cells, clear cytoplasm, and arborizing vessels, and expressed a TFH immunophenotype (CD3+, CD5+, CD7-, CD4+, strong ICOS, and PD1), though CD25 and FOXP3 were also positive." (PMID 37500795, 2023). "Correlation analysis highlighted a co‐stimulatory interaction between lymphoma B cells and CD8+ Tfr cells through the ICOS/ICOSL pathway, which may contribute to a protumor effect." (PMID 41190308, 2025). "LYWS-1061 submitted by Megan Fitzpatrick lacked sufficient TFH marker expression (only CD4 and ICOS) to diagnose TFH lymphoma." (PMID 37500795, 2023). "Conversely, low-grade lymphoma were characterized by the expression of T cell markers (CD3, CD5, the beta chain of the TCR, ICOS, and CD40L) and a follicular dendritic cell marker (CD23), probably reflecting the crosstalk between lymphoma cells and their environment for survival and proliferation." (PMID 32444689, 2020). "In both lymphoma patients and HC, unsupervised cluster analysis showed that levels of naïve T cell populations correlated with the level of induced antibody responses (cluster 2, r = 0.6, p < 0.0001, cluster 11 (CD38+, ICOS+), r = 0.5, p = 0.01, and cluster 3, r = 0.3, p = 0.007)." (PMID 40630518, 2025). "Thus, miR21-mediated p-STAT3 phosphorylation was necessary for the induction of ICOS expression on Treg cells, independent of Bcl-2 expression of lymphoma cells." (PMID 28637496, 2017).
diabetes (11 papers, 2013 to 2025). "In this model, inducible T cell costimulator (ICOS) blockade results in reduced IL-10 secretion by ICOS+ FoxP3+ Tregs and this is associated with exacerbated diabetes." (PMID 23755052, 2013). "In summary, ICOS+ Tregs are the primary cells in pancreatic islets involved in the prevention of diabetes, and any measures to expand these anti-inflammatory cells would efficiently treat diabetes." (PMID 32983168, 2020). "We previously showed in ICOS−/− NOD mice that diabetes protection related with defective activation of effector T-cells." (PMID 28424681, 2017). "Here, we propose an ICOS-dependent mechanism of Treg cell homing to the β-islets during pre-diabetes in the NOD model via upregulation of the CXCR3 chemokine receptor." (PMID 25946021, 2015). "Additionally, ICOS/ICOSL upregulation has been linked to inflammatory responses and endothelial dysfunction in type 2 diabetes mellitus." (PMID 40166070, 2025). "Similarly, ICOS+ Tregs were suggested as a dominant Treg subset to prevent NOD mice from the development of diabetes, and a drastic reduction in ICOS expression on pancreatic Tregs was observed as NOD mice progressed from prediabetic stage to overt diabetes." (PMID 32983168, 2020). "This discovery highlights the crucial role of ICOS from another perspective, as Cxcr3–/– NOD mice developed diabetes earlier than WT mice due to a decreased potential of these Cxcr3–/– Treg cells to migrate from pancreatic lymph nodes to β-islets." (PMID 32983168, 2020). "As we previously reported, both ICOS−/− and ICOSL−/− NOD mice are protected from diabetes but develop a severe neuromyopathy." (PMID 28424681, 2017). "ICOS−/−, ICOSL−/−, and ICOS−/−ICOSL−/− NOD mice were all protected from diabetes and developed neuromyopathy following similar survival curves, but median age of neuropathy was younger in ICOSL−/− (22 weeks) versus ICOS−/− NOD mice (30 weeks, p = 0.008)." (PMID 28424681, 2017). "Strikingly, the transfer of diabetes by CD4+CD25− T-cells was totally ineffective in ICOSL−/− NOD.scid recipients, indicating that ICOS-ICOSL interaction is a prerequisite to the transfer of diabetes by naïve effector CD4+ T-cells from diabetic donors." (PMID 28424681, 2017). "The diabetes protective phenotype observed in ICOS−/− and ICOSL−/− NOD mice thus indicates that the ICOS/ICOSL pathway is directly involved in the T cell activation observed in autoimmune diabetes." (PMID 28424681, 2017). "Abrogation of ICOS/ICOS ligand (ICOSL) costimulation prevents the onset of diabetes in the non-obese diabetic (NOD) mouse but, remarkably, yields to the development of a spontaneous autoimmune neuromyopathy." (PMID 28424681, 2017). "Interestingly, blockade of ICOS and PDL1 was found to negate the regulatory effect of the CD4+ Type II NKT cells in the pancreatic lymph node leading to a sudden development of diabetes." (PMID 24586872, 2014).
parasitemia (11 papers, 2014 to 2025). "It is suggested that M. benedeni infection can promote the expression of ICOS, which lays a foundation for further research on how ICOS regulates the T cell dependent immune response process to exert the immunity against parasitic infection." (PMID 40316996, 2025). "This lays the foundation for future research on the role of ICOS+ T cells in regulating cellular immunity against parasitic infections in different segments of the small intestine." (PMID 40316996, 2025). "Increased parasitemia during peak infection was associated with increased cell frequency and expression of CD38, ICOS and CD86 by Vδ2+ T cells and increased CD86 and HLA-DR by Vδ1+ T cells." (PMID 37968278, 2023). "The importance of the ICOSL:ICOS pathway has been explored in several models of bacterial and parasitic infections." (PMID 33459589, 2021). "Upon depletion of ICOS-expressing T cells by anti-ICOS antibody treatment, we observed prolonged survival of mice with lower parasitemia, suggesting a positive role for ICOS expressing T cells in PbA parasite growth." (PMID 29892278, 2018). "On Day 3, the mean parasitemia in untreated (0.0875 ± 0.025%), anti-ICOS (0.1%), and anti-rat IgG2b (0.1%) treated mice were found to be similar, indicating that infection in all the groups started equally." (PMID 29892278, 2018). "Moreover, data from parasite infection models indicate that IL-4 production by TFH cells not only requires B cells but is dependent on ICOS/ICOSL interactions within the B cell follicle." (PMID 37575256, 2023). "Asymptomatic parasitemia was associated with a significant increase in Ki67 but not ICOS on Tfh cells." (PMID 35851033, 2022). "Thus, in our initial experiment, the depletion of ICOS-expressing cells resulted in significantly lowered parasitemia and prolonged mice survival, suggesting that ICOS positive cells are required for PbA growth." (PMID 29892278, 2018). "Thus, to address the seminal role of ICOS in lethal blood-stage of PbA infection, we treated PbA-infected mice with anti-ICOS antibody and observed that these mice survived longer than their infected counterparts with significantly lower parasitemia." (PMID 29892278, 2018). "Lowered parasitemia, reduced IFN-γ, and increased survival upon anti-ICOS treatment suggest that ICOS plays a role in PbA growth and lethality through IFN-γ production." (PMID 29892278, 2018). "While ICOS deficient mice control the initial parasite load after re-challenge, the absence of ICOS leads to higher relapsing parasitemia compared to wild-type mice." (PMID 32348365, 2020). "Similarly, in this study, upon anti-ICOS administration, depletion of ICOS expressing CD4+ and CD8+ T cells led to lower parasitemia, longer survival, and ameliorated pathology." (PMID 29892278, 2018). "In contrast, during non-lethal blood stage P. chabaudi chabaudi infection, in the absence of ICOS, enhanced Th1 response led to reduced peak parasitemia." (PMID 29892278, 2018). "Costimulatory molecules, such as inducible T cell costimulator (CD278), participate in the activation of FOXP3+ Treg and downregulation of pro-Th2 cytokines at both the local and systemic levels (lymph nodes and spleen) in some parasitic infections." (PMID 28603524, 2017). "Furthermore, anti-ICOS and anti-WSX-1 administration did not significantly alter the level of peripheral parasitemia (up to day 7 of infection, when the experiment was terminated)." (PMID 26459508, 2016).
colitis (10 papers, 2010 to 2024). Inflammation of the colon. "This ICOS mediated sustenance is important as, although ICOS-deficient Treg cells are equally suppressive as wildtype Treg cells in adoptive transfer colitis they eventually cannot prevent mortality in Foxp3 deficient mice." (PMID 34421921, 2021). "Increased ICOS expression is linked to immune deregulation in several human diseases including those of the gastrointestinal tract, in murine colitis and specifically, in Salmonella enterica serovar Typhimurium infection in mice." (PMID 20498845, 2010). "Also, in murine models of colitis and allergy-induced inflammation, increased expression of ICOS and CTLA-4 on Tregs was associated with immune suppression." (PMID 35819849, 2022). "Moreover, ICOS-deficient Treg cells cannot reverse established adoptive transfer colitis." (PMID 34421921, 2021). "To date, many therapeutic approaches have been shown to be effective against colitis in mouse models, most of which function by promoting the expansion and function of intestinal resident Tregs, especially ICOS-expressing Tregs." (PMID 32983168, 2020). "Yet, ICOS Tregs were evident in both steady-state and colitis conditions." (PMID 38085267, 2024). "Indeed, not only are ICOS+ Tregs capable of maintaining T cell tolerance, various FOXP3– regulatory T cells, such as Tr1 cells and Treg-of-B cells, which also express ICOS, can protect mice from experimental colitis." (PMID 32983168, 2020). "However, three ICOS-deficient patients received HSCT due to CID (#12), persistent agranulocytosis (#6) or severe colitis (#15); the latter died following posttransplant complications." (PMID 28861081, 2017). "However, together with the fact that ICOS-deficient Treg cells are equally suppressive as wildtype Treg cells in adoptive transfer colitis it appears that ICOS plays a key role in the stability of intestinal pTreg cells rather than directly regulating suppressive capacity." (PMID 34421921, 2021). "In addition, the frequency of CD4+ICOS+ T cells was also shown to be unexpectedly elevated in non-tumor tissues during treatment with CTLA-4 antibody, causing immune-related adverse events, such as colitis, which should be improved in the future." (PMID 32983168, 2020). "In the present study, the percentages of ICOS+, BCL-6+, PD-1+, and PD-L1+ Tfh cells were downregulated in the peripheral blood of colitis mice treated by SSP, while the number of Blimp-1+ Tfh cells was upregulated." (PMID 32581849, 2020). "On the other hand, a subset of ICOS+ proliferative CD4+ T cells expanded significantly in both those who developed colitis and those who did not." (PMID 36173679, 2022). "In contrast with mice in the DSS group, the numbers of CD4+CXCR5+ BCL-6+, CD4+CXCR5+ICOS+, and CD4+CXCR5+PD-1+ T cells were decreased, and CD4+CXCR5+Blimp-1+ T cells were significantly increased after colitis was treated with SSP and 5-ASA for 7 days." (PMID 32581849, 2020). "For instance, the injection of anti-CTLA-4 mAb was shown to ameliorate trinitrobenzene sulfonic acid (TNBS)-induced colitis by increasing indoleamine 2,3 dioxygenase (IDO) expression and inducing IL-10-producing ICOS+ Treg expansion in the mesenteric lymph nodes and inflamed colon." (PMID 32983168, 2020). "Compared with the normal group, the numbers of CD4+CXCR5+BCL-6+, CD4+CXCR5+ICOS+, CD4+CXCR5+PD-1+, and CD4+CXCR5+PD-L1+ T cells were significantly elevated, while CD4+CXCR5+Blimp-1+ T cells were inhibited in the peripheral blood of colitis mice in the DSS group." (PMID 32581849, 2020). "Although CD69−Tregs also product IL-10 and TGF-β1 and express immunosuppressive molecule such as ICOS, GITR, and CTLA-4, they failed to attenuate DSS-induced colitis and T-cell transfer-induced colitis." (PMID 30185773, 2018).
pulmonary fibrosis (10 papers, 2017 to 2025). Chronic progressive interstitial lung disorder characterized by the replacement of the lung tissue by connective tissue, leading to progressive dyspnea, respiratory failure, or right heart failure. "Studies in SSc mouse models challenged with bleomycin indicated that ICOS-deficient mice were protected from skin and lung fibrosis." (PMID 34986869, 2022). "In addition to Egr1, ICOS has been reported that it isto be positively associated with the amount of ILC2s in the blood of patients with idiopathic pulmonary fibrosis." (PMID 36776864, 2023). "Clinically, the expressions of CD27 and ICOS are enriched in CD8+ T cells within the lung tissues of patients with pulmonary fibrosis." (PMID 41262009, 2025). "Accordingly, increased numbers of ICOS+ ILC2s were detected in the BAL of patients with idiopathic pulmonary fibrosis compared to control subjects, further indicating a relevant function of ICOS signaling in ILC2s in the diseased lung." (PMID 32655549, 2020). "Dysregulated expression of genes, including MMP8, in PBMCs of patients with idiopathic pulmonary fibrosis has been reported, and reduced CD28, ICOS, LCK, and ITK gene expression in PBMCs was associated with poor outcome in cohorts with this disorder." (PMID 29445374, 2018). "Recently, studies have focused on the role of ICOS on adaptive immune responses in lung fibrosis." (PMID 40433386, 2025). "Therefore, regnase-1 is regarded as a crucial posttranscriptional regulator for the pro-fibrotic function of ILC2s in mice and humans, and its regulatory mechanism for Egr1 and ICOS may provide novel therapeutic strategies for idiopathic pulmonary fibrosis." (PMID 36776864, 2023). "4-1BB, PD-1, ICOS and OX40 on T cells bind to 4-1BB ligand, PD-L1/PD-L2, ICOSL and OX40L on antigen presenting cells promote the process of pulmonary fibrosis." (PMID 40433386, 2025). "Using complementary models, we demonstrated that dual ICOS/CD28 blockade by acazicolcept decreased dermal and pulmonary fibrosis and alleviated pulmonary hypertension." (PMID 34986869, 2022). "In order to determine what cytokines and growth factors released from ILC2s contribute to the development of lung fibrosis in HPS, we sorted Lineage– (CD3–CD11b–CD45R/B220–Ly76–Ly6G–Ly6C–), Thy1.2+ICOS+T1/ST2+ ILC2s and examined the gene expression by real-time PCR and RNA-Seq." (PMID 39405112, 2024). "Furthermore, our study demonstrated that the concomitant blockade of both ICOS and CD28 pathways with acazicolcept leads to a significant decrease in dermal and pulmonary fibrosis in two complementary mouse models of SSc." (PMID 34986869, 2022).
bladder cancer (9 papers, 2011 to 2025). "Prior studies have highlighted the importance of ICOS in enhancing combination therapy with anti-CTLA-4 treatments, as seen in bladder cancer patients in whom ICOS-expressing T cells increased after therapy." (PMID 40646580, 2025). "In a neoadjuvant trial for bladder carcinoma with ipilimumab, upregulation of ICOS by TILs as well as circulating lymphocytes was highly correlated with response to therapy." (PMID 28194010, 2017). "Anti-CTLA-4 can drive increased ICOS expression on T cells in clinical trials, and ICOS upregulation on peripheral T cells is correlated with clinical responses to anti-CTLA-4 in bladder cancer." (PMID 31843013, 2019). "Treated with CTLA-4 blockade, ICOS expressed higher on CD4+ T cells from peripheral blood and tumor tissues of bladder cancer patients and this CD4+ICOShi T cell population produced higher IFN-γ, indicating that ICOS interacts with CTLA-4 and plays an important role in tumor immunity." (PMID 21917182, 2011).
pancreatic cancer (9 papers, 2013 to 2025). "High ICOS expression was seen most commonly in esophageal cancer (24%; 4/17) and pancreatic cancer (24%; 13/55) and least commonly observed in sarcoma (4%; 1/24)." (PMID 40297627, 2025). "The CyTOF analysis highlighted senescent T-cells and TIGIT+ICOS+ Tregs as potentially important immune cells in pancreatic cancer." (PMID 33917832, 2021). "However, expression was variable even within tumor types, with 42% of pancreatic cancer showing low levels (<25th RNA percentile rank) of ICOS expression." (PMID 40297627, 2025). "Our analyses revealed that the immune-related genes CCR4, CD19, TNFSF8, SH2D1A, ICOS, IGKV1D-39, and TNFRSF17 may be implicated in the immunophenotyping of pancreatic cancer." (PMID 34737763, 2021). "Several immune checkpoints, including TNFSF4, ICOS, CTLA4, and PDCD1, have been identified as playing crucial roles in the progression of pancreatic cancer." (PMID 37753069, 2023). "For primary pancreatic tumors, late stage (III-IV) PDA demonstrated higher ICOS-PD-1-CD127hiCD8+ (C12) and CD4+ T cells (C10) compared to early stage PDA tumors (Stage I-II)." (PMID 36798126, 2023). "To determine the expression profile of co-stimulatory and inhibitory T cell receptors in the pancreatic tumor microenvironment, we performed multiplex immunofluorescence for CD3, ICOS, LAG-3, PD-1, VISTA, and pan-cytokeratin (PanCK)." (PMID 33803936, 2021). "The results revealed seven immune-related genes (CCR4, CD19, TNFSF8, SH2D1A, ICOS, IGKV1D-39, and TNFRSF17) could potentially influence the immunophenotyping of pancreatic cancer." (PMID 34737763, 2021).
allergic disease (8 papers, 2009 to 2025). An immune response that occurs following re-exposure to an innocuous antigen, and that requires the presence of existing antibodies against that antigen. "We recently published that in humans an ICOS promoter region single nucleotide polymorphism is associated with allergy and increased serum IgE in a founder population." (PMID 19888475, 2009). "Our study newly identified six loci associated with allergic diseases (MIIP, CXCR4, SCML4, CYP1B1, ICOS and LINC00824) and four pleiotropic loci associated with both autoimmune and allergic diseases (PRDM2, G3BP1, HBS1L and POU2AF1)." (PMID 35753705, 2022). "ICOS and IDO1 are proteins related to immunotherapy; relevant target drugs have been produced, and several studies support that they were associated with allergic diseases." (PMID 36077704, 2022). "The results of many recent studies have suggested that ICOS+ Tregs are an activated subset with strong inhibitory ability that can prevent the onset or restrain the progression of most autoimmune and allergic diseases, while they can also contribute to the immunosuppression of tumors." (PMID 32983168, 2020).